CRP (C-reactive protein)
Diseases named in the same sentence as CRP in open-access papers (continued):
Sharing a sentence is not in itself a finding about the gene and the disease.
periodontitis (continued). "As a result, the goal of this study was to compare serum CRP levels and clinical parameters of patients with chronic periodontitis before and after scaling and root planing (SRP)." (PMID 37568846, 2023). "These acute-phase proteins include; C-reactive protein (CRP) and PCT which are significant biomarkers essential for the diagnosis of different forms of periodontitis as periodontitis has been associated with the increased serum levels of these proteins." (PMID 37981665, 2023). "Groupwise comparison revealed significant difference between all groups and also between untreated chronic periodontitis subjects, who demonstrated higher CRP levels compared to SRP treated chronic periodontitis subjects and healthy subjects (p < 0.05)." (PMID 37568846, 2023). "In our study, we observed that severe periodontitis in PLWH is related to higher levels of CRP, higher levels of Pg and higher proportions of senescent CD8 + T-cells." (PMID 36316604, 2023). "CRP is a marker of acute or systemic inflammation, which is released in response to different cytokines (such as IL-6, IL-1, and TNF-α) associated with periodontitis." (PMID 36651310, 2023). "In the current study, patients with moderate periodontitis had higher serum CRP levels as compared to patients with clinical periodontal health." (PMID 38077410, 2023). "The mean serum CRP level in group 1 (subjects with healthy periodontium) at baseline was 0.67 ± 0.55 mg/L and in group 2 (subjects having moderate periodontitis) at baseline was 2.34 ± 0.64 mg/L at baseline." (PMID 38077410, 2023). "IL-6, in turn, can stimulate and release more CRP, which can exacerbate the development of periodontitis by accumulating in the gingival crevicular fluid." (PMID 37481511, 2023). "This cross-sectional study simply found an association between CRP levels and periodontitis in a population classified as obese by BMI, although the relationship between CRP levels and periodontitis has been validated in many studies." (PMID 37481511, 2023). "Periodontitis can be controlled with appropriate periodontal therapy, thereby downregulating systemic CRP levels." (PMID 37479734, 2023). "We also found that the percentage of the CC genotype was lower in the moderate–severe periodontitis group (5%) than in the mild periodontitis group (7.5%) based on the CRP -717 T/C gene." (PMID 37239434, 2023). "Patients with aggressive periodontitis had hs-CRP levels more than 50% higher than patients with chronic periodontitis." (PMID 37711554, 2023). "For periodontitis patients in Group B1, the mean level of C-reactive protein was 1.678 mg/dL and in Group B2 it was 0.8892 mg/dL after SRP." (PMID 37568846, 2023). "A small increase in CRP levels is commonly regarded as an indication of low-grade inflammation, which periodontitis, per definition, is." (PMID 36316604, 2023). "Patients with periodontitis have higher levels of inflammatory biomarkers such as CRP and interleukin-6 in both gingiva and serum." (PMID 38021744, 2023). "On the other hand, periodontal therapy has been shown to reduce plasma levels of interleukin-6, C-reactive protein, and fibrinogen in patients with severe periodontitis and refractory arterial hypertension." (PMID 37509588, 2023). "Second, as a chronic inflammatory condition, periodontitis can also secrete IL-6 and proinflammatory factors as from adipose tissue, which can increase CRP levels." (PMID 37481511, 2023). "The findings of this study show a significant connection between periodontal disease and the inflammatory marker CRP in the body, as well as a tendency for a significant decrease in serumCRP levels following periodontitis therapy." (PMID 38077410, 2023). "The chronic periodontitis population with CAD had the majority of CC, AA, and TT genotypes in IL-6 -572 C/G, CRP -757 A/G, and CRP -717 T/C C/G gene polymorphisms." (PMID 37239434, 2023).
periodontitis (continued). "Periodontitis patients exhibit increased blood CRP levels as well as proinflammatory cytokines such as TNF-α and interleukin-1 in their serum and gingival crevicular fluid (GCF)." (PMID 38021744, 2023). "In individuals with a BMI greater than 30 kg/m2, the prevalence of periodontitis increased as CRP levels rose." (PMID 37481511, 2023). "Compared to healthy controls, patients with periodontitis exhibit elevated serum IL-6 and CRP levels." (PMID 37448125, 2023). "For mild, moderate, and severe chronic periodontitis, the mean CRP values were 1.0, 2.4, and 4.1 mg/l, respectively." (PMID 37575815, 2023). "Elevated levels of inflammatory markers such as CRP, IL-6, IL-1, IL-8, and TNF-α in the blood of patients with periodontitis are thought to be associated with atherosclerotic lesion formation." (PMID 36904268, 2023). "In this point, it will be necessary to consider indices, such as high-sensitivity C-reactive protein levels, which indicates the degree of inflammation in periodontitis." (PMID 35839206, 2022). "Patients with periodontitis had higher CRP levels, while those with gingivitis presented higher gamma-glutamyl transpeptidase levels." (PMID 35866675, 2022). "Patients with severe periodontitis exhibit elevated blood levels of endotoxins (e.g., LPS) and pro-inflammatory markers such as IL-1, IL-6 and CRP." (PMID 35200242, 2022). "Patients with gingivitis and healthy gingiva had lower CRP levels than those with chronic periodontitis." (PMID 36192745, 2022). "Experimental animal periodontitis results in increased serum levels of acute phase proteins (e.g., CRP) and inflammatory cytokines." (PMID 35200242, 2022). "Patients with severe periodontitis have increased levels of pro-inflammatory markers (CRP, fibrinogen, IL-6, IL-1, TNF-α) and neutrophils in the blood and effective periodontal treatment diminishes these inflammatory markers." (PMID 35052857, 2022). "Many studies have shown that periodontitis usually results in higher systemic levels of C-reactive protein, interleukin (IL)-6, and neutrophils." (PMID 35011503, 2022). "According to a 2014 meta-analysis of interventional trials, treatment of periodontitis generally leads to significant decreases in serum levels of CRP, IL-6, TNF-α, fibrinogen, total cholesterol, and a significant rise in HDL-cholesterol." (PMID 35200242, 2022). "Periodontitis triggers systemic repercussions, such as elevated levels of high-sensitive C-reactive protein (hs-CRP)." (PMID 35418117, 2022). "A recent meta-analysis reveals a progressive CRP level reduction up to 6 months in patients with periodontitis following effective treatment." (PMID 35874771, 2022). "In a word, based on the current meta-analysis results, NSPT can significantly reduce serum CRP levels in patients of CAD with periodontitis." (PMID 36243997, 2022). "There is also evidence of higher levels of C-reactive protein (CRP) in periodontitis patients than in healthy subjects and a decrease in CRP levels as an effect of periodontal therapy." (PMID 35951554, 2022). "In this study, NSPT was found to significantly decrease serum CRP levels in CAD patients with periodontitis." (PMID 36243997, 2022). "A cross-sectional study from Thailand revealed CRP (5.2%) and white blood count (19.1%) are mediators of the relationship between periodontitis and impaired fasting glucose." (PMID 35935796, 2022). "On the other hand, the other articles showed significantly higher levels of CRP in patients with periodontitis." (PMID 35225864, 2022). "RA subjects with moderate to severe periodontitis had more categorically severe swollen joints, and higher serum CRP and erythrocytes sedimentation rate (ESR) levels." (PMID 35051027, 2022). "Even though the extent of systemic changes depends on the severity of periodontitis, increased CRP values have also been stated due to experimental gingivitis caused by cessation of oral hygiene." (PMID 36079091, 2022).
periodontitis (continued). "Periodontitis patients have been shown to have elevated blood levels of pro-inflammatory markers, such as C reactive protein (CRP), fibrinogen, IL-6, interleukin-1 (IL-1), and TNF-α." (PMID 36015357, 2022). "Patients with periodontitis exhibit an elevated level of systemic pro-inflammatory mediators, which include CRP, TNFα, IL-1β, IL-6, as well as increased neutrophil numbers in the blood." (PMID 35874771, 2022). "Previous studies have reported that NSPT can significantly decrease CRP levels in periodontitis patients with CVD, which is consistent with our study." (PMID 36243997, 2022). "NSPT has a positive effect on the reduction of serum CRP level in patients of CAD with periodontitis, while limited evidence was obtained that NSPT can positively affect the variation of IL-6, FMD and lipid metabolism parameters." (PMID 36243997, 2022). "While serum hs-CRP concentrations did not significantly differ between groups, patients with gingivitis and periodontitis showed higher CRP levels in GCF, which positively correlated to CRP detection in serum." (PMID 34439905, 2021). "Many previous studies have shown elevated levels of serum inflammatory mediators such as CRP, the tumor necrosis factor-α, and interleukin-6 in patients with periodontitis; these are similar to the inflammatory mediators found in patients with Owt and Ob." (PMID 33603787, 2021). "In general, the literature barely describes GCF CRP variations in gingivitis and periodontitis patients." (PMID 34439905, 2021). "The overall aim of the present systematic review was to critically appraise all up-to-date evidence on the impact of diagnosis of periodontitis on serum CRP levels in otherwise healthy patients when compared to controls." (PMID 34394107, 2021). "Therefore, in patients suffering from CVD as AAA, the concentrations of immunoglobulin G (IgG) against periodontal bacteria, LPS and C-reactive protein (CRP) might be relevant periodontitis-related blood biomarkers to characterize sequelae linked to periodontitis." (PMID 35096635, 2021). "On the basis of our results, the more aggressive forms of periodontitis would be responsible for the greater increase in CRP levels in serum." (PMID 34394107, 2021). "Median CRP levels in gingival crevicular fluid, on the other hand, were significantly raised in gingivitis (1178.2 [2882.5] pg/mL) and periodontitis participants (1131.2 [3667.6] pg/mL) in comparison to healthy women (157 [398.0] pg/mL) (p < 0.001)." (PMID 34439905, 2021). "Conversely, elevated blood levels of CRP or IL-6 are commonly observed in periodontitis, indicating systemic reactions to the local infection and inflammation within the oral cavity." (PMID 32827080, 2021). "Patients with aggressive periodontitis exhibited on average more than 50% higher levels of CRP (RoM [95% confidence interval [CI]]: 1.56 [1.15; 2.12], p=0.0039) than patients with chronic periodontitis." (PMID 34394107, 2021). "The effectiveness of periodontal treatment on CRP levels was also investigated from several reports indicating that CRP was consistently elevated in periodontitis individuals (>2.1 mg/L) compared with healthy controls." (PMID 33804123, 2021). "Patients with gingivitis and periodontitis showed higher levels of CRP in gingival crevicular fluid, which positively correlated to its detection in serum." (PMID 34439905, 2021). "In 2011, a study found that the average serum CRP levels in 50 periodontitis patients were significantly higher than in healthy controls." (PMID 34211440, 2021). "Bacterial lipopolysaccharides from the periodontal regions pass into the bloodstream and initiate the genesis of acute-phase proteins such as the C-reaction protein (CRP) in a patient of periodontitis-type chronic infection." (PMID 34452136, 2021). "C-reactive protein (CRP) elevation is a part of the acute phase response to acute and chronic inflammation and particularly in periodontitis." (PMID 34790237, 2021).
periodontitis (continued). "In the current study, we found statistically higher CRP levels in GCF from individuals affected by both periodontitis and gingivitis, compared to healthy ones." (PMID 34439905, 2021). "Patients with periodontitis reported higher serum CRP levels; however, a CRP systemic and periodontal correlation in gingival crevicular fluid (GCF) and its CVR impact have been barely studied." (PMID 34439905, 2021). "They suggested that elevation in salivary CRP due to periodontitis was overshadowed by differences among examined patients in factors such as the presence of arthritis, the use of anti-inflammatory medications, and the extent of adipose tissue." (PMID 33849511, 2021). "Several large scale cross-sectional studies reported elevated levels of serum CRP in gingivitis and periodontitis." (PMID 33804123, 2021). "The aim of this systematic review was to critically appraise the evidence comparing CRP serum levels (standard and high-sensitivity [hs]) of otherwise healthy patients suffering from periodontitis when compared to controls." (PMID 34394107, 2021). "Publication bias was noted in studies examining CRP levels in patients with periodontitis versus controls (p=0.041) as well as studies comparing the specific diagnosis of chronic periodontitis versus healthy controls (p=0.027)." (PMID 34394107, 2021). "Poor glycemic control (HbA1c ≥ 7%), family history of T2DM, and C-reactive protein levels were predictors of severe periodontitis." (PMID 33924022, 2021). "Indeed, a systematic review reported that a low number of studies controlled for potential confounders, suggesting that the combination of these variables with periodontitis could result in moderately elevated levels of CRP, contributing to an increased risk of CVD." (PMID 34439905, 2021). "Simultaneously, elevated CRP levels aggravate the inflammatory process at the atherosclerotic plaques in patients with periodontitis." (PMID 34452136, 2021). "The increase in CRP concentration reported in patients with periodontitis and the reduction observed following periodontal therapy do not provide a definitive explanation on the pathways by which periodontitis could affect CVD risk but supports this hypothesis." (PMID 34394107, 2021). "Raised levels of pro-inflammatory mediators have been reported in patients with periodontitis who also exhibit distinct hematological changes including raised levels of C-reactive protein (CRP)." (PMID 34394107, 2021). "Compared with the healthy controls, the CRP levels in periodontitis patients are consistently elevated." (PMID 34452136, 2021). "A plethora of case definitions of periodontitis were retrieved as well as variability in the used CRP and hs-CRP methods (i.e., immunoturbidimetry, nephelometry, ELISA, CLIA, RIA, Cardiac-specific claim, latex agglutination method and spectrophotometer)." (PMID 34394107, 2021). "Subjects with extensive periodontitis (≥30% sites with PD ≥ 4 mm) had higher odds ratios for NAFLD than patients with moderate periodontitis (<30% sites with PD ≥ 4 mm) among participants with a serum CRP level <1 mg/L." (PMID 33918456, 2021). "So far, only one meta-analysis had shown high serum CRP levels in periodontitis patients had an average increase of 1.56 mg/L (p<0.001) compared to non-periodontitis cases." (PMID 34394107, 2021). "With periodontal treatment, the symptoms of PPP and periodontitis, high-sensitivity C-reactive protein (hs-CRP) level, and periodontal inflamed surface area (PISA) improved." (PMID 34712500, 2021). "Compared with that of healthy individuals, patients with severe periodontitis have been shown to present significantly increased serum C-reactive protein (CRP) levels." (PMID 34262126, 2021). "Different studies consistently reported higher hs-CRP serum levels in periodontitis and gingivitis patients compared to healthy controls, showing a direct correlation with periodontal inflammation degree." (PMID 34439905, 2021).
periodontitis (continued). "In contrast to previous studies, this review expanded data on both observational and interventional studies liking periodontitis and systemic inflammation though CRP serum levels." (PMID 34394107, 2021). "GCF, CRP levels were significantly elevated in samples of periodontitis patients, as compared to healthy controls." (PMID 34830557, 2021). "In patients with periodontitis, inflammatory biomarker levels such as serum CRP are significantly higher than in healthy persons, while periodontal treatment reduced these levels." (PMID 32827080, 2021). "Some studies found higher CRP levels in GCF of periodontitis patients compared to healthy individuals, but the evidence is scarce and limited, especially regarding gingivitis patients." (PMID 34439905, 2021). "Chronic periodontitis is responsible for the production of C-reactive protein (CRP), interleukin-1b, interleukin 6, TNF-alpha (Tumor Necrosis Factor), as well as the dissemination of these inflammatory mediators throughout the body." (PMID 33143275, 2020). "In patients with aggressive periodontitis, the mean CRP level is higher in generalized aggressive periodontitis (3.72 mg/L) than localized aggressive periodontitis (2.57 mg/L) and controls (1.5 4 mg/L)." (PMID 33424972, 2020). "The aim of this study was to evaluate the relationship between CRP level and the number and proportion of teeth with ≥5 mm pocket depth (PD) in moderate to severe chronic periodontitis patients." (PMID 33424972, 2020). "Individuals with altered C-reactive protein levels showed a higher prevalence of periodontitis than individuals with normal C-reactive protein levels (p=0.008)." (PMID 32994872, 2020). "C reactive protein (CRP) is a marker of acute inflammation, and its levels were found to be high in patients suffering from periodontitis and cardiovascular diseases." (PMID 33456610, 2020). "None of the studies that focused on the relationship between this inflammatory marker and periodontitis included in the present scoping review refers to consecutive measurements of CRP." (PMID 32486269, 2020). "Based on this dichotomous analysis, it is difficult to explain the continuous correlation between the degree of chronic periodontitis and CRP levels." (PMID 33424972, 2020). "The prevalence of periodontitis among individuals with altered CRP (66.7%) was significantly higher than among individuals with normal CRP (37.9%) (P=0.008)." (PMID 32994872, 2020). "C reactive protein was significantly increased in the Periodontitis group on days 1 and 7 compared to both groups." (PMID 33456610, 2020). "Local ozone therapy inhibits the expression of inflammatory factors such as pentraxin-3 (PTX-3), IL-1β, and high-sensitivity C-reactive protein (Hs-CRP) in periodontitis patients." (PMID 32398953, 2020). "This is the reason why regression analyzis assessing the relationship between periodontitis and CRP levels, controlling for these confounders has been conducted herein." (PMID 32994872, 2020). "The alteration of the C-reactive protein levels among individuals with a higher prevalence of periodontitis corroborates clinical evidence that periodontal infection has a systemic impact." (PMID 32994872, 2020). "For that purpose, we measured the serum-levels of cardiac (proBNP, TpI) and inflammatory markers (CRP, IL-6) and compared these values between healthy individuals and periodontitis patients in pre-therapy samples." (PMID 32857064, 2020). "Within the limits of this study, in patients with chronic periodontitis, CRP concentration continuously increased as the number of residual teeth increased." (PMID 33424972, 2020). "The presence of systemic changes can be a confounding factor in assessing the impact of periodontitis on CRP levels." (PMID 32994872, 2020). "There is evidence of significantly higher levels of C-reactive protein (CRP) in periodontitis patients versus healthy controls and in CVD and periodontitis patients compared with either condition alone." (PMID 32489774, 2020).